ISG15 (ISG15 ubiquitin like modifier)
Diseases named in the same sentence as ISG15 in open-access papers (continued):
Sharing a sentence is not in itself a finding about the gene and the disease.
infection (continued). "However, ISG15 levels were not significantly reduced in the cases in which the siRNAs were administered before infection (siRNA/HRSV MOI 3) or when infection at MOI 0.1 was carried out before siRNA transfection (HRSV MOI 0.1/siRNA)." (PMID 31035368, 2019). "Analysis of average infection-induced changes to total proteome abundance revealed that, in contrast to IAV, both IBV and IAVΔNS1 infections triggered a classical host IFN response consisting of several ISG products, including ISG15, ISG20, MDA5, MxA, IFIT1, and IFIT3." (PMID 31391303, 2019). "In BATF3−/− mice lacking CD8α+ DCs, ISG15 fails to induce an IL-1β increase during Toxoplasma infection, as seen in B6 mice, demonstrating that ISG15 induces IL-1β–producing CD8α+ DCs at the site of infection." (PMID 29891555, 2018). "In a neonatal model of infection with chikungunya virus, absence of free ISG15 increases proinflammatory cytokines in the serum, providing the first suggestion that free ISG15 contributes to the host response by regulating cytokine production during infection in the whole organism." (PMID 29891555, 2018). "After triggering specific M1 or M2 polarization, we observed that both ISG15+/+ and ISG15-/- BMDM presented the same levels of inducible nitric oxide synthase (iNOS) (M1 marker) and arginase-1 (Arg-1; M2 marker) protein by western blotting, independently of infection and of the presence of ISG15." (PMID 29077752, 2017). "Interestingly, we found that ISGs such as OAS1 and ISG15 were markedly increased in vaginal tissue of Oasl1−/− mice even in the absence of infection." (PMID 26750802, 2016). "However, ubiquitin was not induced by the infection as observed with ISG15 (i.e., lanes 7, 8 vs. lane 3, 4, respectively)." (PMID 26901217, 2016). "In order to confirm this effect on cytokine secretion under endogenous conditions, we assayed whether ISG15 could modulate cytokine secretion following infection with L. monocytogenes as opposed to L. innocua expressing InlB." (PMID 26259872, 2015). "We have demonstrated that ISG15 restricts infection of nonphagocytic cells." (PMID 26259872, 2015). "Since the block in infection and the differences in viral induced CPE were observed with two very distinct viruses, we next investigated whether other cellular entry processes, such as phagocytosis, might be regulated by ISG15 in macrophages." (PMID 24137104, 2013). "Hence, infection with the mutant virus unable to express the viral kinase ORF47p results in the restoration of IRF3 serine 396 phosphorylation, homodimerization and an enhanced expression of IRF3 target genes such as IFN-β and ISG15." (PMID 21347389, 2011). "In addition viral titers also increase in the absence of ISG15 indicating that ISG15 has an essential role against infection of VACV." (PMID 18604270, 2008). "Additionally, overexpression of murine ISG15 (mISG15), but not a mutant form (mISG15 K151A) that disrupts target protein ISGylation, reduces Sindbis virus replication in IFN-α/β receptor-deficient mice and protects them from lethality following infection." (PMID 40103488, 2025). "Besides functioning as an antiviral effector, ISG15 is a negative regulator of IFN signaling, and inherited ISG15 deficiency leads to autoinflammatory IFNopathies, in which individuals exhibit elevated ISG expression in the absence of pathogenic infection." (PMID 32423918, 2020). "Importantly, loss-of-function mutations in ISG15 have been identified in human patients with subsets of autoinflammatory IFNopathies, and typically, these individuals demonstrate elevated ISG expression in the absence of pathogenic infection." (PMID 32423918, 2020). "H1N1 infection induced IFN-λs, IL-8, IP-10, ISG15, and MDA5 expressions, whilst H3N2 (OK/483) only induced ISG15 and MDA5, and H3N2 (4550) infection showed no immunomodulatory effects." (PMID 40431161, 2025).
infection (continued). "In this study, we observed that mice lacking ISG15 exhibited uterine horn pathology and lower levels of IL-10 in FGT tissue at a later stage of infection." (PMID 40627782, 2025). "It is noteworthy that, in contrast to infection, cells stimulated with IFN-α exhibited only a mild, non-significant release of ISG15." (PMID 40627782, 2025). "Similar to the lab-adapted strains, we observed six ISG-related DAPs (IFIT1, IFIT2, IFIT3, OAS3, ISG15, and MX1) significantly upregulated compared to MOCK infected UNOs, upon infection with clinical isolates of PeV-A3, but not PeV-A1." (PMID 38514653, 2024). "Furthermore, alternating cycles of ISG15+PKCM treatment with ART to nullify viral replication should lead to eventual viral clearance even beyond the latent minimal undetectable viral load to zero non-recurring infection level so that further LRA-PKCM is not required." (PMID 39810915, 2024). "In comparison with those in mock cells, much higher levels of RIG-I and ISG15 were detected in cells with SeV, but no obvious upregulation was observed in cells with PRV1 infection." (PMID 37243262, 2023). "Our results indicate an increase of Isg15, Ifn-I, Il-6 and Pkr mRNA levels at 6 hours after MVA-Δ3-ISG15AA infection but not in the MVA-Δ3-ISG15GG-infected cells." (PMID 37313341, 2023). "ISG15 is strongly upregulated in porcine kidney epithelial cells (PK15) following PRV infection; however, its regulation during infection and the role of ISG15 in viral growth have not been characterized." (PMID 36315588, 2022). "ISG15 mRNA expression increased at 24 h post transfection with Poly (I:C), as previously shown, but not after CVB3/28 infection or CVB-FL/TD50 transfection (p = 0.002)." (PMID 36560784, 2022). "Inhibition of miR-223-3p did not impact levels of CCL2, IFN-stimulated gene 15 (ISG15), or IL-6 in either SARS-CoV-WT or ΔE infection at any time point." (PMID 35229638, 2022). "Again, complementation with WT ISG15 or ISG15ΔGG in C1 ISG15KO cells, but not control C1 cells, increased infection in IFN-I-primed cells." (PMID 35333911, 2022). "Interestingly, analysis of ISG expression indicates that TRIM26 OE cells had no significant increase in MX1 and ISG15 expression after infection, in contrast to WT VK2 and TRIM26 KO cells, suggesting that TRIM26 may have a direct regulatory role for these ISGs." (PMID 33419081, 2021). "While we did not observe differences in IFNAR1, IRF3, STAT1, nor ISG15 expression induced by the two strains, IFNβ, LPG2, RIG1, and OAS1 were significantly induced after infection with Mb3601, but not H37Rv." (PMID 34307535, 2021). "No obvious CPE was observed at 6 hpi in PRV-infected ISG15−/−-PK15 cells; however, the CPE gradually became increasingly apparent as the infection progressed." (PMID 34680952, 2021). "The infection also modifies the expression of MAPK cascade in HCN-2, but in our MSCs, MAPK1 and MAPK3 levels were decreased, and JNK, p38, and ISG15 did not change their values." (PMID 34769246, 2021). "The study is nevertheless limited in its relatively small sample size, assessment of RIG-1, MDA5, ISG-15, and MX1, which was performed in tissue culture, and lack of disease severity assessment after infection." (PMID 34836388, 2021). "The mRNA levels of IFN 1 and its downstream antiviral genes (PKR, ISG15, and MXa) were mildly upregulated in miR-202-5p knockout zebrafish (KO) compared to that in wild type zebrafish (WT) without RGNNV infection." (PMID 32120903, 2020). "We found that ISG15, OASl-1, and RNF185 were induced in A549 cells infected with D39 at 1 h, but not 5 h post-infection." (PMID 30984149, 2019). "Given the effect that ISG15 has on a broad range of viruses, perhaps there is a similar interaction occurring in L929 cells and not in PaKiT03 cells with NBV infection." (PMID 28806913, 2017). "Western blot revealed decreased expression of BST-2/tetherin, but not ISG15, in EV71-infected THP-1 and HT-29 cells at 12 and 24h post infection." (PMID 28910400, 2017).
infection (continued). "We thus measured NO levels in supernatants from ISG15+/+ and ISG15-/- BMDM treated or not with IFN, before and after infection." (PMID 29077752, 2017). "Moreover, we could not detect ISG15 in the supernatant following infection in either cell line." (PMID 26259872, 2015). "In contrast, in macrophages from both ISG15−/− or ISG15+/+ mice, and according to previously published results, the infection with VACV was abortive and viral titers did not increase over time." (PMID 24137104, 2013). "Expression levels of RSAD2, ISG15, IFI44L, and IFI27 were strongly correlated to serum sCD163 levels early after infection, but not to T-cell activation, suggesting that ISG expression may be linked to monocyte activation." (PMID 39104769, 2024). "The other two genes, ISG15 and STAT1, exhibited no considerable (p > 0.05) expression in CT followed by infection, which might be due to the intrinsic nature of the availability of Mx in normal fish species but may not be the case for ISG15 and STAT1." (PMID 36611649, 2022). "Therefore, we investigated expression of IL-15 and ISGs, such as APOBEC3G, ISG15, ISG20, MX1, MX2, and RSAD2, after infection with R5-tropic, non-opsonized (HIV) and complement-opsonized (HIV-C) HIV-1 strains (BaL and YU-2)." (PMID 34634939, 2021). "We found that IFN-λ pretreatment significantly induced the production of ISG54, ISG15, and PKR, while IFN-λ treatment after infection could not effectively activate their expression." (PMID 35185830, 2021). "In addition, IFN‐λ1 mRNA, ISG15, and ISG56 were induced at 9 days after HBV infection, but not mock or ultraviolet‐inactivated HBV (UV‐HBV) infection, in NKNT‐3/NTCP #28.3.25.13 cells." (PMID 32123822, 2019). "However, upon infection, levels of released IFN-γ and IL-1β cytokines were diminished in ISG15−/− mice but not in control C57BL/6 mice or in UbE1L−/− mice, which are devoid of intracellular conjugation of ISG15 through ISG15 E1 enzyme deficiency." (PMID 29891555, 2018). "Moreover, the increase of ISG15 protein levels after VVΔE3L or MVA infection required de novo protein synthesis as its accumulation was prevented by cycloheximide treatment discarding the possibility that infection might increase ISG15 protein levels by enhancing protein stability (not shown)." (PMID 18604270, 2008). "Thus, we hypothesized that the differential expression of Il6 and Tnf during the late stage of infection was not induced directly by NSP9 but rather by other antiviral genes (such as Ifnb, Isg15, and Ccl5) produced via the activated type I IFN pathway." (PMID 37854611, 2023). "In the present study, we observed that several ISGs with known or proposed anti-CCHFV activity, i.e., Mx1, ISG15 and ISG20 or not defined for CCHFV like IFIT1, IFIT3, IFITM3, IFI16, and OAS3 were upregulated in the acute phase CCHFV patient samples as well as in the cell-infection model." (PMID 35437144, 2022). "In addition to IFN-β, we observed that the expression of IFN-α, IL-28, MxA and OASL was also increased in NS1-S212P transfected cells comparing with that in NS1-WT transfected 293T cells after infection with WSN virus, while the expression of IL-29 and ISG15 was not influenced in these cells." (PMID 30285871, 2018). "Because ISG15 is involved in regulating the cell cycle and protein synthesis (shown in this report), an overamplified IFN response (because of lack of ISG15 and reduced levels of USP18) may have led to virus resistance simply because cells were no longer permissive to infection." (PMID 32423918, 2020).
tumor (228 papers, 2006 to 2026). "Elevated ISG15 expression is associated with increased immune checkpoint gene expression, particularly PD-L1, and immune infiltration, notably M2-like tumor-associated macrophages." (PMID 40208307, 2025). "In light of the essential role of ISG15 in tumor immunoregulation, we constructed an ISG15-associated predictive system for ICI response leveraging our proposed machine learning framework." (PMID 40904511, 2025). "This also makes tumor cells with high ISG15 expression more susceptible to cell death when exposed to DNA-damaging drugs." (PMID 41193953, 2025). "In sum, this review examines the functions and mechanisms of ISG15 and ISGylation in various tumor-associated phenotypes, enhancing our understanding of their role in tumorigenesis and disease progression." (PMID 41193953, 2025). "We found that THP1-derived macrophages (THP1-MΦ) cocultured with IFN-β–treated USP5-deficient tumor cells exhibited upregulated ISG15, IFI44, CXCL9, and CXCL10 mRNA expression." (PMID 41321309, 2025). "Functional analysis at the single-cell level revealed significant associations between ISG15 and tumor proliferation, angiogenesis, and immune suppression." (PMID 40208307, 2025). "ISG15 encodes the ISG15 protein, which is involved in multiple cell processes, encompassing cell motility and tumor invasion." (PMID 40904511, 2025). "As discussed in the previous chapter, LFA-1 can adversely influence tumor progression through its interaction with interferon-stimulated gene 15 (ISG15), which activates tumor-associated macrophages (TAMs)." (PMID 39911389, 2025). "In the context of pancreatic ductal adenocarcinoma (PDAC), extracellular ISG15 was found to be secreted by tumor-associated macrophages which enhanced cancer stem cell phenotypes in PDAC and promoted tumor growth in mice." (PMID 40719862, 2025). "Elevated levels of ISG15 and increased ISGylation have been associated with various malignancies, where they promote tumor cell survival, stemness, and metastatic potential." (PMID 40103488, 2025). "The anti-tumour effect of ISG15 was directly associated with the cytotoxic potential of antigen-specific stimulated CD8 T cells." (PMID 38400136, 2024). "In vivo, Isg15 deficiency in MC38 tumor cells almost completely abolished the therapeutic effect of CV-1." (PMID 38982116, 2024). "Pearson correlation analyses were conducted to evaluate correlations between ISG15 expression and tumor-associated factors." (PMID 38644421, 2024). "Although animals in both groups showed analogous body weights, the ISG15-knockdown mice indicated obviously lower rates of tumor volume, which associated with lower levels of ISG15." (PMID 37501099, 2023). "The induction of ISG15 and ISGylation is associated with tumor treatment efficiency, including chemotherapy and radiotherapy." (PMID 36771004, 2023). "For instance, ISG15-mediated tumor stemness was shown to be the important cause of cisplatin resistance in ovarian cancer." (PMID 37501099, 2023). "Previous studies have demonstrated that ISG15 secretion is increased in M2 or activated macrophages, which is tightly associated with tumor growth as well as angiogenesis, tissue remodeling, and suppression of adaptive immunity." (PMID 36771004, 2023). "Interferon-stimulated gene 15 (ISG15) is a ubiquitin-like modifier, associated with tumour progression, and with poor survival of SFT patients, as previous published by our group." (PMID 35864381, 2022). "Functionally, this agrees with observations from cancer research that overexpression of ISG15 in tumor cells is associated with increased cell migration." (PMID 34847081, 2022). "Several other studies based on clinical data have associated high ISG15 expression with unfavourable prognosis in cancer patients, as well as with higher histological grade, tumour size or invasiveness." (PMID 35864381, 2022). "In xenograft models, ISG15 knockdown reversed enlarged tumor size and poor mouse prognosis caused by YAP overexpression." (PMID 35149670, 2022).
tumor (continued). "Vaccination with ISG15 confers regression of HPV-associated tumor burden in mice, providing new insight into the immunomodulatory properties of ISG15 and its potential to serve as an effective immune adjuvant in cancer therapies." (PMID 36319753, 2022). "The most highly overexpressed of all proteins, interferon-stimulated gene 15 (ISG15), was more recently also associated with tumor progression." (PMID 34674701, 2021). "Interferon-stimulated gene 15 (ISG15) encodes ISG15 (ubiquitin-like protein) which is highly expressed in almost all tumours and is stimulated by type I interferons." (PMID 33073304, 2021). "Although numerous studies have demonstrated that ISG15 is essential for tumor metastasis, its function in PCa metastasis and the underlying molecular mechanism are not fully understood." (PMID 34696780, 2021). "ISG15 expression was associated with tumour size (P < 0.001), pTNM stage (P < 0.001), and lymphatic metastasis (P = 0.038)." (PMID 32641707, 2020). "Three possible biomarkers associated with CNS metastases in TNBC tumours were identified: ISG15, THBS1 and AP1M1." (PMID 30792808, 2019). "ISG15 is also a stress-response gene that has been implicated as a tumor suppressor and contributor to inflammatory responses." (PMID 30641486, 2019). "The ubiquitin-like modifier interferon-stimulated gene 15 (ISG15) is implicated in both oncogenic and tumor suppressive programs." (PMID 27980214, 2017). "Dysregulated expression of ISG15 was linked to resistance to radiation and chemotherapeutics in tumor cells, suggesting ISG15 was a biomarker for drug sensitivity." (PMID 29296177, 2017). "This is consistent with the clinically significant finding that high ISG15 expression was associated with more frequent tumor recurrence and shorter survival in NPC." (PMID 26919245, 2016). "ISG15 expression is significantly associated with the differentiation grade, metastatic of tumor and survival of HCC patients." (PMID 25238261, 2014). "Our analysis of tumor formation in 10 weeks old mice revealed that the number of lesions of different sizes was significantly reduced in an Isg15-deficient background." (PMID 25071020, 2014). "Overexpression of ISG15 in tumor cells has been linked to reduced protein polyubiquitylation and turnover." (PMID 21298066, 2011). "It willbe of great interest to explore the role of ISG15 in tumor suppression and age-associatedinflammatory condi-tions, and finally to identify additional genes and pathwaysregulated by telomere length and how they impact human biology." (PMID 20157543, 2009). "Each of these roles has been implicated in carcinogenesis, although ISG15 was recently thought to function as an oncogene as well as a tumour-suppressor gene." (PMID 18627608, 2008). "ISG15 exhibited a stage-associated expression, with significantly (P<0.05) higher levels of ISG15 protein in muscle-invasive T2–T4 tumours, compared with normal urothelium." (PMID 16641915, 2006). "The levels of expression were highly stage-associated, as ISG15 protein increased through the tumour stages Ta, T1, to T2–T4." (PMID 16641915, 2006). "We demonstrated that PRDM6 expression occurs almost exclusively in tumor cells of clinical HNSCC tissues and that PRDM6 promotes proliferation and growth of HNSCC tumor cells in vitro while suppressing expression of anti-tumor ISGs (ISG15, IFITM1) by both loss- and gain-of-function approaches." (PMID 40936897, 2025). "In pancreatic cancer, free ISG15 may be implicated in maintaining the stemness of tumor cells by increasing the phosphorylation level of ERK1/2." (PMID 36771004, 2023). "Besides, ISG15 can be a crucial microenvironmental factor in this malignancy, as tumour-associated macrophages can secrete ISG15, increasing CSC phenotype in tumour cells." (PMID 35864381, 2022).